SLIT3 (slit guidance ligand 3)
Diseases named in the same sentence as SLIT3 in open-access papers (continued):
Sharing a sentence is not in itself a finding about the gene and the disease.
triple-negative breast carcinoma (1 paper, 2022). An invasive breast carcinoma which is negative for expression of estrogen receptor (ER), progesterone receptor (PR), and human epidermal growth factor receptor 2 (HER2). "Here, we have shown the N-terminal SLIT3 protein induces growth suppression of four triple-negative breast cancer cell lines." (PMID 36361532, 2022).
tuberculous meningitis (1 paper, 2025). "Finally, SLC1A1 and SLIT3 variants were associated with susceptibility to tuberculous meningitis and subsequent survival, respectively, in a Vietnamese cohort." (PMID 40402573, 2025).
Usher syndrome (1 paper, 2012). A syndromic diseae characterized by the association of sensorineural deafness (usually congenital) with retinitis pigmentosa and progressive vision loss. "Several of the top candidate genes include EEF1A1, ROBO1, PLXNA4, SLIT3, NRP1, and NOTCH2, as well as genes associated with the Usher syndrome, PCDH15 and USH2A, and are plausible candidates contributing to the developmental defects in Gbx2−/− mice." (PMID 23144817, 2012).
cancer (35 papers, 2004 to 2025). A tumor composed of atypical neoplastic, often pleomorphic cells that invade other tissues. "miR-218 is encoded within intronic sequences of SLIT2 and SLIT3, which act as a tumor suppressor gene in many cancers." (PMID 27285984, 2016). "In contrast, the 176 passager genes were biased toward functions developed with cancer progress, such as their top genes, SCN4B and SLIT3, which controlled cancer cell migration, and the ABCA8 gene that related to cancer chemoresistance." (PMID 38666214, 2024). "Among them, the slit guidance ligand 3 (SLIT3) gene is highly methylated, especially in late-stage cancer tissues." (PMID 39479352, 2024). "The tumor suppressive role of SLIT3 has been shown to inhibit cancer cell growth and invasion and migration in several tumors." (PMID 36752296, 2023). "We have shown that ectopic SLIT3 treatment of cancer cells elevates the expression of the receptor ROBO2, suggesting a positive feedback loop." (PMID 36361532, 2022). "SLIT3, ABI3BP, MYOCD, PGM5, TNXB and DNAH9 are strongly associated with cancer initiation and progression." (PMID 36451444, 2022). "The promoter hypermethylation of SLIT2 and SLIT3 genes results in the down‐regulation of miR‐218 expression in cancer cells." (PMID 33107676, 2020). "SLIT3 hypermethylation has been reported in a number of human cancers, and SLIT3 expression is increased in LPS-stimulated macrophages in mice." (PMID 28143570, 2017). "miR-218 is an intronic miR of SLIT2 and SLIT3, which are epigenetically silenced in different cancer cells and tissues." (PMID 27462788, 2016). "SLIT2 and SLIT3 are commonly found to be silenced by aberrant DNA hypermethylation in promoter regions in cancers." (PMID 26610476, 2015). "Downregulation of miR-218 in cancer cells has been shown to be caused by promoter hypermethylation of SLIT2 and SLIT3 genes." (PMID 23483249, 2013). "Slit3 is a secreted protein whose family is known to regulate migration of neural cells, and its downregulation seems implicate in progression of various cancers." (PMID 23593401, 2013). "The downregulation of miR-218 in cancer cell was caused by promoter hypermethylation of SLIT2 and SLIT3 genes." (PMID 23159910, 2012). "SLIT3 suppresses cancer cell migration and angiogenesis via ROBO signaling." (PMID 40564222, 2025). "In certain tumors, limited evidence suggested that SLIT3 might be involved in the activation of cancer-promoting signaling pathways such as the ERK/MAPK and GSK3β/β-catenin signaling pathways." (PMID 39479352, 2024). "Epigenetic inactivation of SLIT3 has been found in human cancers." (PMID 32299382, 2020). "Additionally, Slit3 has been shown to suppress tumor growth in mouse models and impairs cancer cell invasion and migration, suggesting that Slit3 functions as a tumor suppressor in a variety of cancers." (PMID 29859044, 2018). "In addition, EMT-related microRNAs were noted, including miR-218-2, which was frequently repressed and co-methylated with its host gene SLIT3; miR-214, which targets EZH2, β-catenin, and BIRC7 —all were genes implicated in cancer metastasis and invasion; miR-382, which targets ROR1." (PMID 30922328, 2019). "Similarly, the fold change of SLIT3 in cancer vs. normal tissues was 0.16 (p = 8.9 × 10−16)." (PMID 28830450, 2017). "We discovered many genes (SLIT3 and HSPG2) which were co-expressed with COL15A1 across various cancers and tissues using STRING and GEPIA2." (PMID 39088036, 2024). "These merged DMxDE datasets suggest some known or previously reported/suspected cancer genes [PR: SPARCL1, NQO1, CST1, MELK1, DPT, FAM83A, MMP9; GB: FOXM1, TFAP2, GREM1, ITGA8, GRIA1, SLIT3] as well as many previously unreported genes/loci." (PMID 26683690, 2015). "In this report, we analysed the methylation status of 5′ CpGs islands for the remaining SLIT gene family members (SLIT3 and SLIT1) in human cancers." (PMID 15534609, 2004).
cancer (continued). "Recent findings have shown that SLIT3 appears to function as a novel tumor suppressor gene in various types of cancers, yet its clinical correlation and role in HCC has not been understood clearly." (PMID 29859044, 2018). "However, a comprehensive analysis addressing the clinicopathological and predictive significance of SLIT3 in cancers, particularly in LUAD, is still lacking." (PMID 36752296, 2023). "Also, HOPX was correlated with genes in a manner toward suppression of cancer cell progression; downregulation of TNRC6C, PAX8, TSHR, DYRK1A/B, and SLIT3 (pro-proliferation/migration), and upregulation of PCDH8/9, CDC42EP3/4/5, and TJP3 (anti-proliferation/migration)." (PMID 31666923, 2019). "However, we found a number of established drivers of cancer progression and invasion (e.g., mTOR, STAT1/5, RHOC, ARF6, HMGB, and CRK) with increased expression levels as well as known suppressors (e.g., AIFL1 and SLIT3) with decreased expression levels upon PTEN inhibition." (PMID 36555834, 2022). "Slit3 down-regulation in HCC might indicate a poor response of the tumor cells to chemotherapy, and subsequently, treatment with recombinant Slit3 is a novel potential therapeutic approach in patients with HCC, as well as other cancer types where Slit3 is repressed." (PMID 29859044, 2018).
tumor (34 papers, 2004 to 2025). "In order to validate the association between Slit3 expression and HCC tumor size, we investigated the Slit3 gene expression in another cohort of HCC patients (N = 25)." (PMID 29859044, 2018). "We investigated the methylation status of this 5′ CpG island associated with the SLIT3 gene in various human tumour cell lines." (PMID 15534609, 2004). "In tumour cell lines, silenced SLIT3 associated with hypermethylation and was re-expressed after treatment with 5-aza-2′-deoxycytidine." (PMID 15534609, 2004). "SLIT3 is also associated with tumor proliferation, migration, and invasion." (PMID 36835855, 2023). "SLIT3, which is enriched in the Stage 4S-specific tumor cell subpopulation, acts as a potential differentiation inducer functioning through PLCβ/PKC signaling." (PMID 40448172, 2025). "Our study revealed that SLIT3 regulates tumor cell differentiation through the PLCβ/PKC signaling pathway, providing novel mechanistic insights and available therapeutic targets for clinical translation." (PMID 40448172, 2025). "In our study, we identified elevated SLIT3 expression in a Stage 4S-specific tumor cell subpopulation, suggesting its potential as an auxiliary diagnostic marker for Stage 4S, and an indicator of spontaneous regression." (PMID 40448172, 2025). "Given the robust differentiation-inducing capacity and consistent prominence in Stage 4S tumor and cluster cIVS, SLIT3 was selected as the primary candidate for subsequent functional validation." (PMID 40448172, 2025). "Collectively, these results suggested that SLIT3 expression in a subset of tumor cells was sufficient to suppress tumor growth and promote tumor differentiation in vivo." (PMID 40448172, 2025). "Our study provides more substantial evidence directly proving the tumor-suppressive role of SLIT3 in the progression of NSCLC." (PMID 39479352, 2024). "Consistent with the RNA-Seq data, validation of DEGs expression by qRT-PCR and GEPIA cohort showed that FHL1 and SLIT3 were down-regulated in LUAD patient tissues compared with non-tumor tissues." (PMID 36752296, 2023). "To identify differentially methylated CpGs at the promoter regions of SLIT genes, we analyzed methylation statuses of SLIT1, SLIT2 and SLIT3 genes in tumor and matched normal tissues from 42 NSCLC patients previously reported." (PMID 35053460, 2022). "SLIT3 is a gene characterized by axon guidance and consequently tumor growth, migration, and angiogenesis." (PMID 34417465, 2021). "MiR-218-5p, a vertebrate-specific intronic miRNA co-regulated with its host genes SLIT2/SLIT3, functions as a tumor suppressor by modulating multiple pathways." (PMID 30699189, 2019). "Slit3 overexpression was found to significantly repress Hep3B tumor growth in mice when compared with Hep3B-pcDNA cells (250.5 mm3 vs 3975.3 mm3, p = 0.001)." (PMID 29859044, 2018). "This study suggests that Slit3 acts as a tumor suppressor in HCC by repressing the tumor growth and thus tumor progression." (PMID 29859044, 2018). "Within the high Slit3 expression group, 55% (N = 11) of the patients had a large tumor (size > 5 cm), and this number significantly increased to 85% (N = 17) within the low Slit3 expression group (p = 0.048)." (PMID 29859044, 2018). "These clinical findings in combination with the functional studies suggested that Slit3 plays an important role in inhibiting tumor growth and progression in HCC." (PMID 29859044, 2018). "Our results demonstrated a repression in Slit3 expression in nearly 50% of the HCC patients, while the overall expression of Slit3 inversely correlated with the size of the tumor in both cohorts of patients." (PMID 29859044, 2018). "Restoration or overexpression of Slit3 is a potential therapeutic approach to repress the tumor growth and enhance the efficacy of chemotherapeutic agents." (PMID 29859044, 2018).
tumor (continued). "Subsequently, we sorted the patients into high and low Slit3 groups as per the median (tumor/non-tumor) Slit3 expression (low≤ Fold change = 1.203 > high) and compared their clinicopathological parameters." (PMID 29859044, 2018). "Taken together, results from both the HCC patient cohorts showed that the expression of Slit3 in HCC inversely correlated with the size of the tumor." (PMID 29859044, 2018). "Stable down-regulation of Slit3 in HCC cell-lines induced cell proliferation in vitro and tumor growth in vivo, while stable Slit3 overexpression repressed these effects." (PMID 29859044, 2018). "We determined the transcript levels of Slit3 in tumor and adjacent normal tissues within two cohorts (N = 40 and 25) of HCC patients, and correlated the gene expression with the clinicopathological data." (PMID 29859044, 2018). "Statistical analyses using Fisher exact test showed that Slit3 expression correlated with the HCC tumor size." (PMID 29859044, 2018). "In line with the in vitro effects, Slit3 repression significantly induced tumor growth in mice (1054.9 mm3 vs 48.2 mm3, p = 0.002)." (PMID 29859044, 2018). "Different from the significant inhibitory effect on tumors for SLIT2, SLIT3 remains controversial in the progression versus suppression due to tumor species specificity." (PMID 27974673, 2017). "To further investigate lung tumorigenesis, we also analyzed the expression of SLIT2 and SLIT3 since miR-218 co-expresses with these host tumor suppressor genes." (PMID 28830450, 2017). "The miR-218 transcripts are located within the introns of SLIT2 (pri-mir-218-1) and SLIT3 (pri-mir-218-2), which were reported to function as tumor suppressors." (PMID 24705471, 2014). "By day 29, the SLIT3-expressing group exhibited significant tumor growth suppression compared to the Ctrl group, demonstrating the in vivo capacity of SLIT3 to suppress tumor growth." (PMID 40448172, 2025). "Also, we identified novel predicted tumor-suppressive ligands (SLIT3, DCN, CCN3, THBS1, INHA and INHBA), proteins (DNASE1L3, SULF1, PTEN, OAS1, and DAB2IP), and receptors (P2RX4, CDHR2, PTPRJ, and PTPRH) in MSC1 cells." (PMID 40564222, 2025). "Mechanistically, SLIT3 induces tumor cell differentiation through the PLCβ/PKC signaling." (PMID 40448172, 2025). "Consistent with our in vitro findings, A549-bearing mice treated with IT3 siRNAs exhibited a rapid tumor growth curve and shortened survival time compared to the scramble group, indicating that the SLIT3/UBE2C/Wnt axis promotes NSCLC progression and chemoresistance." (PMID 39479352, 2024). "It was noted that downregulated SLIT3 was related to advanced tumor stage and poorer prognosis." (PMID 39479352, 2024). "Our study identified the tumor-suppressive role of SLIT3 in NSCLC." (PMID 39479352, 2024). "The tumor cells with silenced SLIT3 showed increased resistance to PTX and Cis." (PMID 39479352, 2024). "Due to the pro-tumor effects and chemoresistance development, chemotherapy was applied in combination with a Wnt inhibitor (Wnt-C59) to treat the A549-bearing mouse model with silenced SLIT3." (PMID 39479352, 2024). "It was observed that dysregulated SLIT3 expression might affect tumor biology and behaviors, including tumor proliferation, migration, apoptosis, and tumor-related angiogenesis." (PMID 39479352, 2024). "On the other hand, the expression of p27 which is a negative regulator of cell cycle progression was lower in LM3-shSlit3 versus shCTL tumor, and stronger in Hep3B-Slit3 versus pcDNA tumor, showing that a higher expression of Slit3 suppressed cell cycle progression of HCC cells." (PMID 29859044, 2018). "The results from the patient samples indicated a potential tumor suppressive role of Slit3 in HCC." (PMID 29859044, 2018).
tumor (continued). "Moreover, the effect of Slit3 alteration on tumor growth in vivo was more obvious than that on in vitro cell proliferation, which was possibly due to the effect of Slit3 on tumor angiogenesis as demonstrated by the CD31 immunohistochemical staining." (PMID 29859044, 2018). "Moreover, we found that Slit3 repression inversely correlated with tumor size, which was subsequently reaffirmed in the in vitro and in vivo experiments which showed that Slit3 negatively regulated HCC cell growth." (PMID 29859044, 2018). "This study showed that Slit3 was a potential tumor suppressor in HCC." (PMID 29859044, 2018). "Taken together, these results indicated that Slit3 negatively regulated HCC tumor growth in vivo." (PMID 29859044, 2018). "Within the high Slit3 expression (>Fold change = 0.593) group, 50% of the patients (N = 6) showed a large tumor (size > 5 cm), while the percentage significantly increased to over 90% (N = 12) in patients with low Slit3 expression (≤Fold change = 0.593; p = 0.003)." (PMID 29859044, 2018). "Furthermore, the downregulation of SLIT3 was related to a higher tumor stage and poorer prognosis." (PMID 39479352, 2024). "Moreover, this research further verified that the SLIT3/UBE2C axis could mediate tumor cell proliferation and migration via Wnt3A/β-catenin signaling pathway activation." (PMID 39479352, 2024). "Our functional studies revealed that SLIT3, a key ligand in the SLIT-ROBO signaling, promotes tumor cell differentiation and suppresses tumor growth via intratumoral crosstalk." (PMID 40448172, 2025). "In comparison to tumor vasculature in MVP and CT regions, SLIT3, COL8A1, LUM and POSTN showed enhanced spatial enrichment within the GBM hyperplastic region." (PMID 41366031, 2025). "Slit3 was frequently down-regulated in HCC tumor tissue and its expression inversely correlated with tumor size." (PMID 29859044, 2018). "We tested the effect of Slit3 repression on the response of HCC cell lines to sorafenib, an oral multikinase inhibitor that executes its antitumor activities by blocking tumor angiogenesis, targeting the Raf/Mek/Erk pathway and inducing cell apoptosis." (PMID 29859044, 2018). "Secondly, miR-218 host genes SLIT2 and SLIT3 promoters are hypermethylated in the majority of CRC cell lines and tumor specimens." (PMID 27462788, 2016). "In the network, Slit2 and Slit3 were redundantly activating Robo1, Robo2, Robo4 and ITGA1 receptors in tumor." (PMID 24597571, 2014). "We analysed the 5′ CpG island of SLIT3 and SLIT1 genes in tumour cell lines and primary tumours for hypermethylation." (PMID 15534609, 2004). "Silencing SLIT3 expression played a tumor-promoting role in A549 and NCI-H1299 cell lines, suggesting that SLIT3 may act as a tumor suppressor gene in NSCLC." (PMID 39479352, 2024). "The impact of SLIT3 on NSCLC growth was assessed in vivo by establishing a subcutaneous A549-bearing mouse model with or without SLIT3 silencing and recording tumor volume and mouse survival." (PMID 39479352, 2024). "Moreover, five genes, including the SLC12A4, SLIT3, GYPC, TSPAN4, CYYBRD1, CYB5R3, and FBLN5 were identified as co-expressed in the healthy and tumor tissue groups." (PMID 37365287, 2023). "Five CpGs at the CpG island of SLIT1, SLIT2 or SLIT3 genes were significantly (Bonferroni corrected p < 0.05) hypermethylated in tumor tissues obtained from 42 NSCLC patients than in matched normal tissues." (PMID 35053460, 2022). "In line with the results obtained in the first cohort, Slit3 down-regulation (tumor/non-tumor< 1) was frequently observed 56% (N = 14) of the patients." (PMID 29859044, 2018). "Though they demonstrated that Slit3 was not differentially expressed, 4 of the 8 tumor-adjacent normal tissues showed Slit3 repression in the HCC tissue, suggesting that Slit3 repression was present in half of the HCC patients." (PMID 29859044, 2018).
tumor (continued). "In this front, we wanted to investigate the clinical relevance of the SLIT2 and SLIT3 promoter methylation in metachronous metastasis positive and negative tumor specimens of CRC patients." (PMID 27462788, 2016). "Furthermore, in tumor tissues from NSCLC patients, we identified a notable negative correlation between SLIT3 expression and UBE2C levels." (PMID 39479352, 2024). "Based on TCGA-LUAD transcriptome data, differential expression analysis showed that with the comparison of normal samples, DKK1 and LOXL2 expression were significantly increased in tumor tissues, whereas MGP and SLIT3 were markedly overexpressed in non-tumoral tissues." (PMID 36185284, 2022).
psychiatric disorder (2 papers, 2020 to 2022). A disorder characterized by behavioral and/or psychological abnormalities, often accompanied by physical symptoms. "SLIT3 has also been shown to play a critical role in the formation and maintenance of the nervous system, indicating a generally shared genetic association among psychiatric disorders." (PMID 35912095, 2022). "Whilst speculative, it is also potentially of relevance that HTR1A protein expression is upregulated in the brains of schizophrenics and variants in both HTR1A and SLIT3 are associated with psychiatric disorders, known to involve dopaminergic and serotoninergic pathways." (PMID 32209227, 2020).
myopathies (1 paper, 2025). "In this regard the SLIT3 gene, belonging to the axon guidance pathway, was the most upregulated gene in breasts affected by SM and WB; interestingly, its upregulation has been suggested to be highly correlated with myopathies." (PMID 40841884, 2025).
neurodegenerative disease (1 paper, 2010). A disorder of the central nervous system characterized by gradual and progressive loss of neural tissue and neurologic function. "Each region also included key genes associated with addiction (Maoa, Ptprd, and Slit3), psychiatric illnesses (Maoa, Myt1l, Slc12a6, and Slit3), and neurodegenerative diseases (Apba1 and Slc12a6)." (PMID 20808911, 2010).